TSHR (thyroid stimulating hormone receptor)
Diseases named in the same sentence as TSHR in open-access papers (continued):
Sharing a sentence is not in itself a finding about the gene and the disease.
Obesity (26 papers, 2012 to 2025). Accumulation of substantial excess body fat. "The ablation of TSHR in mice resulted in decreased adipogenesis and caused the resistance to high-fat-diet-induced obesity." (PMID 34574358, 2021). "The TSHR expression in adipose tissues is associated with diet- induced obesity in mice and increases with increasing BMI in human." (PMID 22289392, 2012). "In the present study, TSHR expression in adipose tissues from both mice and human was analyzed, and its association with obesity was evaluated." (PMID 22289392, 2012). "TSHR knockout animals were predisposed to obesity development." (PMID 34574358, 2021). "Our findings suggest that dysregulated TSHR expression might be implicated in obesity development under certain circumstances, which may involve a mechanism of excess adipogenesis." (PMID 22289392, 2012). "Dysregulated expression of TSHR in adipose tissues is associated with obesity, which may involve a mechanism of excess adipogenesis." (PMID 22289392, 2012). "However, it remains unclear whether TSHR expression in adipocytes is implicated in the pathogenesis of obesity." (PMID 22289392, 2012). "It is also important to remember that individuals suffering from obesity exhibit reduced expression of the TSHR and TRα1 genes in adipose tissue." (PMID 33808030, 2021). "A previous study showed that in white adipose tissue, the thyroid hormone receptor (TRA1) and the TSH receptor (TSHR) of obese individuals were reduced in proportion to the extent of obesity." (PMID 34524974, 2021). "In obesity, the expression level of thyroid stimulating hormone receptor in adipose tissue is reduced and the levels of thyroid stimulating hormone (TSH) are often elevated within the normal range." (PMID 32812397, 2020). "More recent studies report a positive correlation between TSHR activation and obesity, and reports using animal models suggest a role for the TSHR in BAT and WAT function." (PMID 28469599, 2017). "To investigate the possible involvement of TSHR in the pathogenesis of obesity, we analyzed the TSHR expression profile in adipose tissues in mice." (PMID 22289392, 2012). "We generated obesity mice (C57/BL6) by high-fat diet feeding and found that the TSHR protein expression in visceral adipose tissues from obesity mice was significantly higher in comparison with the non-obesity control mice (P < 0.05)." (PMID 22289392, 2012). "In TSHR knockdown mice, the expression of genes responsible for fatty acid synthesis and triglyceride storage was downregulated and animals exhibited resistance to high-fat-diet-induced obesity." (PMID 34574358, 2021). "Animals partially lacking functional TSHR in AT were more susceptible to developing obesity compared to corresponding WT mice." (PMID 32812397, 2020). "Non-synonymous mutations in thyroid stimulating hormone receptor (TSH-R) gene also plays a role in elevated TSH levels in relation to obesity." (PMID 33117269, 2020). "Whilst it is conceivable that increasing TSHR concentration in obesity may attract additional release of TSH through a positive feedback to the pituitary, direct data in this regard are currently unavailable." (PMID 24913450, 2014). "In addition, we determined the TSHR expression in adipose tissues from both mice and human samples, and the relevance of TSHR expression in adipocytes to obesity was evaluated." (PMID 22289392, 2012). "Given the notable detrimental effects on metabolism observed in our KO model, these data suggest that TSHR down‐regulation in obesity may contribute in the manifestation of a range of metabolic abnormalities, including glucose intolerance, altered adipokine profile, and dysfunctional thermogenesis." (PMID 32812397, 2020). "Finally, TSHR protein expression in visceral adipose tissue was analyzed, and results showed that the average TSHR protein level in obese mice was higher compared to the non-obesity control mice." (PMID 22289392, 2012).
Obesity (continued). "These researchers indicated that elevated TSH reduces energy expenditure and promotes adiposity, while mice lacking TSHR showed higher metabolic rates and were resistant to obesity." (PMID 34574358, 2021).
thyroid nodule (24 papers, 2011 to 2025). A small circumscribed mass in the THYROID GLAND that can be of neoplastic growth or non-neoplastic abnormality. "Mutations in TSHR have already been identified in the context of feline thyroid disease, more precisely, in the thyroid nodules of hyperthyroid cats; however, the role of TSH-related genes have never been explored in feline thyroid tumors." (PMID 40711277, 2025). "There have been at least two studies looking specifically at the clinicopathological correlation of TSHR variants in indeterminate thyroid nodules (ITN)." (PMID 36619548, 2022). "A clear outlier in this review is a study that deliberately selected indeterminate nodules with TSHR mutations identified by molecular diagnostic testing of indeterminate thyroid nodules." (PMID 33632297, 2021). "A recent series reported an increased risk of malignancy in TSHR-mutant functional thyroid nodules when TSHR mutations occur at high allelic frequency." (PMID 32632840, 2020). "In the first and pivotal study by the Brussels lab in 1993, 9 out of 11 toxic thyroid nodules harboured an activating TSHR mutation." (PMID 32303903, 2020). "Utilization of ThyroSeqV.2 in all indeterminate cytology gives us an opportunity to find thyroid nodules harboring TSHR mutations and/or NIS overexpression." (PMID 30319546, 2018). "It indicated that this mutation would account for a major genetic alteration of TSHR in thyroid nodules and be more common than we used to anticipate." (PMID 30319546, 2018). "In addition, transcriptomic data was used to screen feline thyroid nodules for mutations in TSHR and GSα." (PMID 39567583, 2024). "As most literature describes TSHR mutated nodules as benign and when malignant, low risk, a query was made to Veracyte, Inc regarding the prevalence and risk of malignancy of TSHRpI568T mutated thyroid nodules." (PMID 36619548, 2022). "However, the precise mechanism that drive the evolution from thyrocytes harbouring a gain-of-function TSHR mutation to a clinically apparent toxic thyroid nodule are still far from being understood, adding to the ongoing discussion that additional alterations may be required." (PMID 32303903, 2020). "It allows us to investigate the clinical significance and diagnostic utility of TSHR mutations and/or NIS overexpression detected in pre-operative thyroid nodules with an indeterminate cytology." (PMID 30319546, 2018). "In view of these findings, it should be noted that TSHR mutations and NIS overexpression are closely associated with thyroid nodules, in particular with AFTNs." (PMID 30319546, 2018). "Our study demonstrated that TSHR mutations and/or NIS overexpression occurred in a higher than expected 6.4% of 388 consecutively biopsied thyroid nodules with indeterminate cytology." (PMID 30319546, 2018). "Though our study provided a novel perspective to understand the clinical significance of TSHR mutations and/or NIS overexpression in thyroid nodules, due to some limitations, results of this study need to be applied with caution." (PMID 30319546, 2018). "Accordingly, the purpose of detecting TSHR mutations and/or NIS overexpression in thyroid nodules was different between our study and former researches." (PMID 30319546, 2018). "Somatic mutations in Gsα, and in TSHR gene, are the main reason for autonomously functioning, TSH-independent, thyroid nodules in iodine-deficient regions of the world." (PMID 28410400, 2017). "The expression of TSHR mRNA in the circulating cells has also been shown to enhance preoperative detection of cancer in patients with thyroid nodules." (PMID 26684026, 2016). "The role of methylation status of the thyroid stimulating hormone receptor gene (TSHr) in the discrimination of benign and malignant thyroid nodules has already been studied using paraffin blocks and cell lines." (PMID 26519197, 2015). "In our study, we found that a significant number (over half) of patients with thyroid nodule showed TSHr methylation using cytological material." (PMID 26519197, 2015).
thyroid nodule (continued). "As cytological sampling plays an important role in assessment of thyroidal nodules, we have investigated the potential clinical use of TSHr methylation status of fine needle aspiration specimens reported according to Bethesda System." (PMID 26519197, 2015). "In addition, TSHR, TTN, PIK3CA, and EIF1AX mutations in thyroid nodules categorized as indeterminate are uncommon and are typically verified as benign." (PMID 40586006, 2025). "TSHR CAMs are also found in up to 80% of toxic thyroid nodules and toxic multinodular goiters." (PMID 38194289, 2024). "The naturally occurring TSHR p.I640V mutation has not been reported, but a mutation in the same position (p.I640K) has been described in a patient with a hot thyroid nodule and increased (up to 5.9-fold) basal cAMP activity compared with the WT receptor." (PMID 38194289, 2024). "TSHR mutations have also been found occasionally in functional and rarely in non-functional malignant thyroid nodules." (PMID 30319546, 2018). "GRK4 was overexpressed in hyperfunctioning thyroid nodules (HTNs) compared with their adjacent tissues but failed to induce thyroid-stimulating hormone receptor (TSHR) desensitization, which may cause HTN." (PMID 35769816, 2022). "Unlike the other test-methods, TSHR mRNA blood assay doesn't require an FNA sampling of the thyroid nodule." (PMID 28472764, 2017). "Unlike previous studies which checked somatic genetic alterations of TSHR and NIS using surgically resected thyroid tissue from known autonomous nodules, the distinction of our study was having these molecular alterations detected in pre-operative thyroid nodules with indeterminate biopsy." (PMID 30319546, 2018).
thyroid tumor (19 papers, 1996 to 2025). A benign or malignant neoplasm affecting the thyroid gland. "Although the expression of ERBB2 was positively correlated with that of TSHR, the role of TSHR in radioiodine refractoriness remains debated because the highly expressed TSHR is not only associated with high radioiodine uptake but also causes fast thyroid tumor growth." (PMID 36437939, 2022). "Upon labeling with the radionuclide 99mTc, TR1401 has strong imaging capabilities in TSHR-positive cell lines, TSHR-positive thyroid tumor models, and poorly differentiated DTC models." (PMID 40532044, 2025). "TSHR methylation evaluation in thyroid tumors has demonstrated the hypermethylation of TSHR promoter in 33% of thyroid cell cancers and 30% of adenoma cases." (PMID 37560303, 2023). "TSHR gene promoter is relatively rich in CpG dinucleotides, and it is believed that the changes in DNA methylation determine TSHR gene silencing in thyroid tumors." (PMID 36013156, 2022). "Taken together, these data suggest that SH promoted the redifferentiation and increased the RAI uptake of thyroid tumor cells by upregulating the TSHR/cAMP signaling pathway in BCPAP and TPC-1 cells." (PMID 36142613, 2022). "This study showed the importance of TSHR gene methylation and its significant association with BRAFV600E mutation in thyroid tumors, depicting a positive correlation between TSHR pathway and MAP Kinase pathway." (PMID 28117293, 2017). "Thus, strengthening interdisciplinary cooperation, such as combining biology, medicine, and materials science, is crucial for accelerating the application of nanomaterials in TSHR-targeted thyroid tumor therapy." (PMID 40532044, 2025). "Notably, TSHR expression exhibits an inverse correlation with the differentiation status of thyroid tumors." (PMID 41153734, 2025). "Thus, detecting individualized levels of TSHR and their changes in thyroid tumors is crucial for developing therapies and determining patient prognosis." (PMID 40532044, 2025). "Although substantial research focused on examining circulating mRNA as potential diagnostic biomarkers of thyroid neoplasms, Tg and TSHR mRNA have not been widely accepted as accurate and valid biomarkers of thyroid neoplasms." (PMID 37547301, 2023). "Likewise, the active response to TSH via TSHR/cAMP-mediated signaling in differentiated thyroid tumors is critical because TSH is used to induce radioactive iodine uptake." (PMID 33176626, 2021). "A significant was observed between TSHR gene methylation and positive BRAFV600E mutation cases (P < 0.05), suggesting that TSHR gene methylation is highly correlated with the BRAFV600E mutation in thyroid tumours and that TSHR pathways are positively correlated with MAP kinase pathways." (PMID 34923978, 2021). "TSHR and KCNJ16 were downregulated in the thyroid tumor tissues, compared with paired normal tissues." (PMID 37208644, 2023). "However, the responsiveness of thyroid tumors to TSH stimulation demonstrates substantial heterogeneity, likely attributable to variations in TSHR expression levels and functionality." (PMID 41153734, 2025).
follicular carcinoma (16 papers, 1997 to 2025). "Mutations in the TSHR gene can alter receptor function and contribute to the development and progression of follicular thyroid cancer." (PMID 39744583, 2025). "Mutations in the TSHR gene (thyroid-stimulating hormone receptor) are an important genetic biomarker in follicular thyroid cancer." (PMID 39744583, 2025). "The remaining malignant clustered adenoma showed a TSHR mutation previously associated with autonomously functioning follicular carcinomas." (PMID 33383892, 2020). "Among the TSHR mutations we found, the p.I486F has been previously associated with an autonomously functioning follicular carcinomas whereas p.D633Y mutation has been reported in a toxic metastasizing FC, an Hurthle cell carcinoma, and in a pediatric PTC." (PMID 33383892, 2020). "We describe, for the first time, a mutation in TSHR contributing to follicular thyroid carcinoma (FTC) in an adolescent." (PMID 30416831, 2018). "Also frequently mutated was TSHR, found in 6/75 (8 %) of histology benign samples and only once in a malignant follicular carcinoma." (PMID 26818556, 2016). "TSHR gene transfection contributes to the redifferentiation of dedifferentiated thyroid follicular carcinoma cells." (PMID 40532044, 2025). "In fact, TSHR stimulation induced expression of metallothionein isoform 1X (MT1X) in human follicular carcinoma cells." (PMID 28923001, 2017). "There were no cases of follicular adenomas with a positive methylation status of TSHr(0/4) whereas in 3 of 6 (50 %) follicular carcinomas TSHr’s were found to be methylated." (PMID 26519197, 2015). "An inconsistency in TSHR expression data for FTC-133 cell lines derived from lymph node metastases of differentiated follicular thyroid carcinoma across different laboratories has been noted, which may be attributable to genetic drift or epigenetic changes occurring during cell line passaging." (PMID 40532044, 2025). "TSH is a growth factor for papillary and follicular thyroid cancer, and successful TSH suppression therapy assumes a functional TSH receptor (TSHR) in thyroid cells whose activity is minimized by the dearth of circulating TSH." (PMID 25292307, 2015). "Our findings are consistent with a prior study wherein 10 mU/mL of b-TSH failed to induce proliferation in human thyroid follicular carcinoma cells that were transfected to overexpress functional TSHR." (PMID 39061242, 2024). "Signaling of WT-TSH and mutants was tested in the thyroid follicular carcinoma cell line FTC-133 (lacking endogenous TSHR expression) that were stably transfected with TSHR." (PMID 31703413, 2019). "Upon adapting the culture conditions to better mimic the human physiological environment, the follicular thyroid carcinoma cell line FTC-238, derived from a lung metastasis, exhibited a marked upregulation of TSHR expression, whereas no such change was observed in 8305C cells." (PMID 40532044, 2025).
thyroid dysgenesis (16 papers, 2014 to 2025). "Five TSHR variants including two novel variants were identified in patients with thyroid dysgenesis from five families." (PMID 40391015, 2025). "TSHR genetic defects can cause poor differentiation (thyroid dysgenesis) and/or thyroid malfunction (THD)." (PMID 39337518, 2024). "Genetic defects in the TSH receptor (TSHR) can cause poor thyroid differentiation (thyroid dysgenesis) and/or thyroid malfunction (thyroid dyshormonogenesis)." (PMID 39337518, 2024). "AIM: To assess the frequency of incidence of pathogenic variants of the TSHR gene in children with CH due to thyroid dysgenesis." (PMID 36842079, 2023). "Mutations in the TSHR gene are mostly associated with thyroid dysgenesis, and prevent or disrupt normal development of the gland." (PMID 37561783, 2023). "The TSHR gene is predominantly related to thyroid dysgenesis, as most of the mutations occurs in the gene in CH patients." (PMID 37561783, 2023). "The findings will be helpful to realize the molecular etiology of thyroid dysgenesis (TH) via exploring the mutational impact for TSHR protein and suggest more efficient treatment strategies including suitable drug design in future." (PMID 37561783, 2023). "Additionally, 21.21% (28/132) of mutations were related to thyroid dysgenesis [TSHR (n = 19), TTF1 (n = 5), TTF2 (n = 1), PAX8 (n = 2), and NKX2-5 (n = 1)]." (PMID 30420871, 2018). "The associated hypothyroid phenotype is variable depending on the type and location of the variants and how much TSHR function is affected, from euthyroid state and partial thyroid dysfunction (mild/borderline hypothyroidism) with a normal thyroid gland to severe CH with thyroid dysgenesis." (PMID 40391015, 2025). "While the disease usually occurs sporadically, familial cases of thyroid dysgenesis are associated with homeobox genes, including TTF-1, TTF-2, PAX-8 and TSHR." (PMID 39857886, 2025). "The existing data suggest that inactivating mutations in the TSHR gene are responsible for thyrotropin (TSH)resistance and thyroid dysgenesis." (PMID 26758695, 2016). "Primary congenital hypothyroidism (CH) due to thyroid dysgenesis may be mediated by defects in thyroid transcription factors or impaired thyroid stimulating hormone receptor function." (PMID 35999191, 2022).